CD4 (CD4 molecule)
Diseases named in the same sentence as CD4 in open-access papers (continued):
Sharing a sentence is not in itself a finding about the gene and the disease.
AIDS (continued). "The added immune deficiency syndrome due to HIV depletion of CD4 T-cells may explain the high parasite density among people living with HIV/AIDS as indicated in the current study." (PMID 31354844, 2019). "Statistical analyses revealed an association between miR‐375 changes and CD4 cell counts, which could explain the discordant cases and the opposite trend between asymptomatic and AIDS‐KS patients." (PMID 30549196, 2019). "The HIV GWG variant was associated with higher CD4 levels and time of AIDS." (PMID 31335686, 2019). "The virus carrier can develop severe immunodeficiency since CD4+ T lymphocytes are the main target, leading to acquired immunodeficiency syndrome (AIDS)." (PMID 31531340, 2019). "CD4+ count <200cells/μL poses the greatest risk for opportunistic infection in HIV/AIDS patients." (PMID 32546916, 2019). "Three surveillance databases in Brazil (notification of HIV/AIDS cases, CD4 cell counts, ART dispensations) have been linked with vital registration data to provide information on over one million PLHIV, tracking individuals from diagnosis, through laboratory tests, treatment programmes and death." (PMID 30819120, 2019). "The late stage involves a sudden increase in viral load with a drastic decrease in CD4 + T cell counts leading to AIDS (acquired immunodeficiency syndrome) which is characterized by opportunistic infections and malignancies." (PMID 30966844, 2019). "Furthermore, immunodeficiency, identified by lower CD4 cell counts, was also strongly associated with liver‐related non‐AIDS death." (PMID 30615271, 2019). "We hypothesize that HIV/AIDS disease progression marked by reduced CD4+ count will be associated with significantly reduced antioxidant enzymes activities and trace element levels in Ghanaian patients." (PMID 31339937, 2019). "However, there continues to be an association of a lower risk of AIDS and death with a higher CD4 cell count, even above 500 cells/mm3." (PMID 30531492, 2019). "Furthermore, analysis of the distribution of all patient characteristics according to the RQ levels demonstrated an association between RQ and CD4 levels, that was statistically significant in naïve and treated AIDS‐KS patients." (PMID 30549196, 2019). "Effector memory CD4+ T cells are the primary targets of HIV-1 and their depletion parallels the development of the acquired immune deficiency syndrome." (PMID 30873181, 2019). "The analysis showed that although the CD4+ T-cell level and the decline in the level were independently associated with progression to AIDS, only the CD4+ T-cell level or a combined CD4+ T-cell level/decline stratification was associated with the rate of HIV-2 evolution." (PMID 30622192, 2019). "In the AIDS epidemic, CD4+ T lymphocytes deficiency renders HIV/AIDS patients less resistant to cryptococci, thus the rise in cases of human cryptococcosis was followed by the increasing diagnosis and morbidity of HIV/AIDS despite the development of antiretroviral therapy." (PMID 31333658, 2019). "In this study, we developed the prototype of an optical imaging-based point-of-care (POC) device for monitoring human immunodeficiency virus (HIV)/acquired immunodeficiency syndrome (AIDS) progression that can detect CD4+ T-lymphocytes in human blood." (PMID 30875995, 2019). "Higher CD4 count (101 to 200 cells/μL: aSHR = 0.61, 95% CI 0.42 to 0.90, p = 0.011; >200 cells/μL: aSHR = 0.23, 95% CI 0.17 to 0.33, p < 0.001) compared to CD4 ≤ 100 cells/μL was also associated with lower non‐AIDS mortality." (PMID 30615271, 2019). "HIV is a retrovirus that depletes CD4+ cells and strongly impairs the immune response, thus opening up the way for opportunistic infections that cause the acquired immunodeficiency syndrome (AIDS)." (PMID 30254568, 2018). "Clinical AIDS and a lower CD4 at baseline were predictive of an increased risk of death." (PMID 29569354, 2018).
AIDS (continued). "The virus gradually reduces the number of CD4+ T cells in the infected patient, which impairs the human immune system and eventually leads to acquired immunodeficiency syndrome (AIDS)." (PMID 30619232, 2018). "HIV-1 primarily infects CD4+ T cells, consequently compromising the individual’s immune defense and leading to acquired immunodeficiency syndrome (AIDS)." (PMID 30510929, 2018). "Acquired immune deficiency syndrome (AIDS) refers to HIV clinical stage 3 or 4 disease or, where CD4 is available, any clinical stage and CD4 < 350 cells/mm3 (WHO 2005:10)." (PMID 31934391, 2018). "Residual systemic chronic immune activation persists more in INRs and contributes to CD4+ T-cell low recovery with a higher rate for progression to acquired immunodeficiency syndrome (AIDS) (Paiardini and Müllertrutwin, 2013)." (PMID 30034377, 2018). "Consistent with this evidence, some studies suggest that the cART might lead to a marked decrease in immune activation and increased CD4+ T cell counts in ECs, reducing the risk of non-AIDS-related events." (PMID 30050532, 2018). "Notably, the extent of mucosal CD4 T-cell depletion in pathogenic SIV infection of rhesus macaques determines the rate of progression to AIDS." (PMID 30326919, 2018). "Co-infected patients were more likely to have acquired HIV through injecting drugs use (57.4% vs. 1.1%), to be women, older, and Spanish, have a lower educational level, and having started ART with lower CD4 counts and acquired immunodeficiency syndrome." (PMID 30235668, 2018). "The high rate of persistent CD4:CD8 ratio abnormality despite ART that we report may have significance for future non-AIDS morbidity and mortality, including diseases associated with ageing in yp-PaHIV." (PMID 29465561, 2018). "CD4+ T cells are believed to be necessary for the initiation of psoriatic skin lesions; however, the exacerbation of psoriasis is observed in acquired immunodeficiency syndrome (AIDS) upon CD4+ T cell depletion." (PMID 29180838, 2017). "The START study recently showed that HIV infected individuals have a considerably lower risk of developing AIDS or other serious complications when antiretrovirals are started earlier in their disease course, even when they are asymptomatic and have higher CD4 counts." (PMID 28744377, 2017). "Loss of CD4 T cells has long been known as the major pathological event leading to AIDS." (PMID 29250073, 2017). "HIV infects CD4+ T cells and is responsible for acquired immune deficiency syndrome (AIDS)." (PMID 28981470, 2017). "With respect to HIV coreceptor tropism, R5 viruses usually predominate during primary HIV infection, whereas the transition to X4 viruses occurs in later stages of HIV disease, being associated with more rapid CD4+ T-cell depletion and consequently to AIDS progression." (PMID 29257103, 2017). "These limitations of therapy resulted in most guidelines suggesting that treatment should be deferred until patients were at high risk for the development of acquired immunodeficiency syndrome (AIDS)-associated complications, such as when CD4 cell counts were less than 200 cells/μL." (PMID 28649373, 2017). "This is highlighted by the increased susceptibility of acquired immune deficiency syndrome (AIDS) patients (who have low numbers of CD4+ T cells) to C. parvum infection, and ability of the parasite to cause chronic infections in MHC class II deficient mice (which lack functional CD4+ T cells)." (PMID 28800747, 2017). "The death of CD4+ T cells cripples the immune system and increases the susceptibility of the host to opportunistic infections—a condition known as acquired immunodeficiency syndrome (AIDS)." (PMID 28620380, 2017). "Depletion of CD4+ T cells has been described as the primary cause for terminal progression to AIDS." (PMID 29259605, 2017).
AIDS (continued). "Recently published report demonstrating the progressive bilateral fusiform intracranial aneurysms in a child with human immunodeficiency virus/acquired immunodeficiency syndrome, in which CD4-positive T cell subset is affected, indicates such a possibility." (PMID 28437485, 2017). "Factors associated with PCS were CD4+ count < 200 cells/mm3 (β = -5.84, 95% CI: -7.63, -4.06), mental comorbidity (β = -2.82, 95% CI: -3.79, -1.85), medical comorbidity (β = -2.51, 95% CI: -3.75, -1.27), AIDS diagnosis (β = -2.38, 95% CI: -3.79, -0.98)." (PMID 28591161, 2017). "The study also showed a significantly higher risk of MI with a low CD4 cell count (<200 cells/mm3) indicating that HIV/AIDS with lower CD4 cell counts might further contribute to cardiovascular complications." (PMID 28716008, 2017). "However, PLWH on ART with CD4 count >350 cells/μL and suppressed VL experience higher mortality than the general population, mainly due to non-AIDS causes." (PMID 28903507, 2017). "Aberrant turnover of memory CD4+ T-cells is central to Acquired Immunodeficiency Syndrome (AIDS) progression." (PMID 27227993, 2016). "There is now increasing evidence to show that patients failing to achieve CD4+ T-cell counts >500 cells/μl are at increased risk of developing serious non-AIDS events, including cardiovascular disease, hypertension, liver disease, non-AIDS malignancies and neurocognitive impairment." (PMID 27438728, 2016). "In addition, it was also observed that those whose CD4 testing frequency increased one time per 6 months was associated with 80% reduction in the hazard of AIDS-related mortality (aHR 0.20, 95% CI = 0.17–0.23)." (PMID 27324204, 2016). "However, HIV/AIDS positive individuals with reduced CD4 count, <200 cells/μl, showed a significant association with HBsAg seropositivity." (PMID 26855663, 2016). "The human immunodeficiency virus type 1 (HIV-1) infection is characterized by a continuous viral replication in CD4+ T lymphocytes and macrophages, ultimately leading to the development of the acquired immunodeficiency syndrome (AIDS)." (PMID 26973648, 2016). "This ultimately leads to Acquired Immune Deficiency Syndrome (AIDS), a condition characterized by loss of CD4+ T cells, profound immunodeficiency, and susceptibility to serious opportunistic infections." (PMID 26950141, 2016). "IMPORTANCE HIV-1 causes AIDS by spreading within immune cells and depletion of CD4 T lymphocytes." (PMID 27558417, 2016). "Because generalized immune hyperactivation is strongly associated with high viral loads, loss of CD4+ T cells and therefore AIDS progression, Vpr-mediated NFAT activation might be a determinant of HIV-1 pathogenesis." (PMID 27383627, 2016). "Although HIV-1 within-host evolution has been associated with clinical factors used to monitor AIDS progression, such as patient age, CD4 cells count, viral load, and antiretroviral experience, little is known about the role of these clinical factors in determining between-host HIV-1 evolution." (PMID 27907076, 2016). "Under these circumstances, it is important that research participants fully appreciate the risks including drug resistance, the risk of transmission to sexual partners, severe primary infection-like symptoms, reduced CD4 count and increased risk of cardiovascular events and AIDS-related events." (PMID 27137204, 2016). "Study of a clinic case reveals that alpha-1-antitrypsin (AAT) deficiency is related to CD4+ T cell count decline and AIDS progression, suggesting that AAT might be an endogenous inhibitor of HIV/AIDS." (PMID 27473095, 2016). "Moreover, sexual behavior such as early sexual debut and ≥5 lifetime sexual partners predicted prevalent HPV and so did variables associated with a compromised immune system such as CD4 < 350 cells/μL and AIDS prior to inclusion." (PMID 27821088, 2016).
AIDS (continued). "Whether these effects of N-Vpu contribute to viral pathogenesis remain to be determined, but it is noteworthy that HIV-1 N strains can cause CD4+ T-cell depletion and AIDS (44, –, 46)." (PMID 27531907, 2016). "Human Immunodeficiency Virus (HIV) infection and Acquired Immunodeficiency Syndrome (AIDS) is characterized by progressive CD4+ T cell depletion in patients’ peripheral blood and lymphoid tissues." (PMID 27042825, 2016). "In summary, physicians who care for HIV-infected patients should be aware that AIDS-associated BL may unusually present as rapidly growing bilateral orbital masses in adult patients with very low CD4 cell counts." (PMID 27818811, 2016). "It has been shown that the risk of AIDS-associated BL declines steeply at very low CD4 cell counts, suggesting that its expression may require functional CD4 lymphocytes." (PMID 27818811, 2016). "In addition, it was also observed that those whose CD4 testing frequency increased one time per 6 months was associated with 81% reduction in the hazard of AIDS-related mortality (aHR 0.19, 95% CI = 0.17–0.20)." (PMID 27324204, 2016). "HIV-1 is a lentivirus that infects several different types of immune cells, but primarily CD4+ positive T cells, and causes AIDS, a condition that is characterized by immune suppression, and AIDS patients are at high-risk of opportunistic microbial infections, including cancer-causing viruses." (PMID 26797638, 2016). "HAD is an Acquired Immune Deficiency Syndrome (AIDS) defining illness associated with poor clinical outcome, low CD4 count, high viral load, low haemoglobin, and poor adherence to ART." (PMID 26347017, 2015). "Other studies, instead, focused on the important role of JCV-specific CD4+ T cells in the control of JCV infection based on the knowledge of the increased risk of PML in AIDS patients with low levels of CD4+ lymphocytes, and in patients with idiopathic CD4+ lymphocytopenia." (PMID 25972864, 2015). "Previous work has postulated that deficiency of CD4+ T-cell-mediated immunity plays a key pathogenic role in AIDS patients and may also be involved in immunocompromised HIV-negative patients, potentially leading to Penicillium marneffei infection." (PMID 26573268, 2015). "Similar to defining how HIV destroys CD4 T-cells and causes AIDS via using an antiviral drug, one can decipher the molecular pathway that restores memory CD4 T-cell function against HIV infection, reconstituting patient anti-HIV immunity in vivo via an anti-inflammatory drug or immunotherapy." (PMID 26300920, 2015). "HIV-1 infection is associated with immunological dysfunctions characterized by an abnormal hyper-activation of the immune system, a selective depletion of CD4+ T-cells and an increase in the production of pro-inflammatory cytokines associated with fast progression of the infection towards AIDS." (PMID 26090662, 2015). "Thus, the need for a reliable and economic point of care (POC) diagnostic for the count of CD4+ T cells is a fundamental tool in the fight against HIV/AIDS." (PMID 25622041, 2015). "This is reminiscent of recalcitrant HPV infection in HIV+ individuals, including increased severity of disease and higher rates of HPV-associated cancer as CD4+ T cell counts drop and AIDS progresses, although there are clearly many of additional immune deficits in these patients." (PMID 26495972, 2015). "The majority of cases involving MAC infection of the CNS are seen as opportunistic infections in patients with acquired immunodeficiency syndrome (AIDS) with a severely depressed CD4 count (<50 cells/μl)." (PMID 26201464, 2015). "In this study, we demonstrated that in for the subsample of deceased AIDS patients in three Chinese provinces, only those who initiated cART while at a CD4 count ≥200 cells/mm3 were less likely to die from AIDS-related causes compared to those who didn’t initiate ART at all." (PMID 26506621, 2015).
AIDS (continued). "Human immunodeficiency virus-1 (HIV-1) which causes acquired immune deficiency syndrome (AIDS), by infecting CD4+ immune cells and hence weakening the host defense mechanism till death, is one of the major factor responsible for human demises worldwide." (PMID 26322257, 2015). "Adaptive immune responses mediated by CD4+ T cells play a critical role in controlling the progress of M. tuberculosis infection, as HIV/AIDS patients whose CD4+ T cells are deficient are more susceptible to M. tuberculosis(MTB) infection than are HIV-uninfected individuals." (PMID 26018190, 2015). "In addition, SMART, a randomized trial, demonstrated that patients who deferred ART until their CD4 cell counts dropped to <250 cells/mm3 had a higher risk of AIDS- and non-AIDS-related events than those who initiated therapy immediately." (PMID 25908935, 2015). "Risk factors associated with mortality in our study were lower CD4 count, older age and clinical AIDS at ART initiation, which have been reported in other regional settings and a large meta-analysis of 50 studies from low- and middle-income countries in Asia, Africa, and Central and South America." (PMID 26165322, 2015). "Different from immunocompetent individuals or those with other T cell immune deficiencies, AIDS patients with CM often present a CSF minimal cellularity related to advanced immunossupression, as corroborated by the CD4+ T cells baseline count < 100 cells/mm3 observed in 76.7% of individuals." (PMID 25799044, 2015). "Both viral setpoint and CD4 count have been used as proxy measures of virulence, since the former predicts rate of progression and the latter indicates risk of opportunistic infections; indeed, a CD4 count of <200 cells/mm3 is one definition of AIDS." (PMID 26834742, 2015). "To identify possible reasons for the increased rates and accelerated kinetics of AIDS progression in elderly individuals, we analyzed which properties may render CD4+ T cells from the elderly particularly susceptible to HIV-1 infection and depletion." (PMID 26452480, 2015). "Risk factors for death were clinical AIDS at baseline (adjusted hazard ratio (HR)=1.65 (95% CI 1.47–1.87); p<0.001), lower baseline CD4 (HR=1.95 (95% CI 1.63–2.32) for 50 vs. 350 cells/μL; p<0.001) and older age (HR=1.47 (95% CI 1.29–1.69) for 50 vs. 30 years at ART initiation; p<0.001)." (PMID 26165322, 2015). "In conclusion, our results suggest that a low CD4/CD8 ratio might identify a subset of individuals at increased risk of non-AIDS-associated morbidity and mortality." (PMID 24497929, 2014). "Higher initial CD4 cell counts were associated with better outcomes, with the greatest benefit evident in patients with an initial CD4 cell count above 500 cells/mm3 (HR 0.19 for AIDS CI95 0.11-0.30, p = 0.000; HR 0.32 for death CI95 0.10 - 0.97, p = 0.044)." (PMID 25523753, 2014). "Bystander apoptosis of neighbouring uninfected cells appears to encompass an explanation for most of the phenomenon observed during HIV infection that leads to progression to AIDS and remains one of the leading hypothesis for CD4+T-cell loss." (PMID 24963975, 2014). "Compared to CD4 responders, patients with immuno-virological discordance may be at increased risk of developing non-AIDS events." (PMID 24498036, 2014). "Finally, HBV vaccine has prognostic value in the setting of HIV infection as vaccine responders have been shown to have a reduced risk of developing AIDS and death, including those with CD4 counts >500 cells/uL." (PMID 25144773, 2014). "Since we restricted the definition of non-AIDS events to ischemic heart disease, stroke, end-stage kidney disease, and non-AIDS malignancies, we cannot provide information on the value of the CD4/CD8 ratio to identify subjects at higher risk of other non-AIDS conditions." (PMID 24497929, 2014).